WNK1 (WNK lysine deficient protein kinase 1)
Diseases named in the same sentence as WNK1 in open-access papers (continued):
Sharing a sentence is not in itself a finding about the gene and the disease.
tumor (38 papers, 2010 to 2026). "Lysine-deficient protein kinase-1 (WNK1) is critical for both embryonic angiogenesis and tumor-induced angiogenesis." (PMID 36292952, 2022). "Ectopic expression of miR-93 in TNBC cell line by suppression of WNK1 (WNK lysine deficient protein kinase 1) attenuated invasion and migration of tumor cells." (PMID 35499045, 2022). "Studies have shown that tumor tissues with higher Fuhrman nuclear grade express a high level of WNK1, while WNK1 protein is rarely detected in lower grade tumors." (PMID 37576896, 2023). "The role of With-nolysine kinases 1 (WNK1) in tumorigenesis is partly achieved by stimulating tumor cell proliferation." (PMID 37652923, 2023). "In a study on the human intrahepatic CCA cell lines HuCCT-1 and SSP-25, UA treatment-induced G2/M phase cell cycle arrest, thus repressing cell proliferation, and exerted anti-tumor effects by suppressing the Akt/WNK1 signaling pathway and inducing autophagy." (PMID 36673365, 2023). "Increasing evidence indicates the roles of WNK kinases which are represented by WNK1 in tumorigenesis by stimulating tumor cell proliferation." (PMID 35368686, 2022). "From the viewpoint of tumor xenograft angiogenesis, WNK lysine-deficient protein kinase 1 (WNK1), a regulator for sodium and chloride ion channels, is downstream within the VEGF signaling cascade." (PMID 35326412, 2022). "Incubated with tumor cell-conditioned medium from WNK1-knockdown and/or miR-524-5p-overexpressed CRC cells, the migratory ability and the number of capillary-like structures in hECs were significantly reduced." (PMID 36123332, 2022). "By in vitro and in vivo experiments, we further uncover the molecular mechanisms of WNK1 and its downstream effectors during tumor-induced angiogenesis." (PMID 36292952, 2022). "Endothelial-specific overexpression of WNK1 enhanced tumorigenesis in transgenic carcinogenic zebrafish, supporting endothelial cell-autonomous effect of WNK1 in tumor production." (PMID 35813203, 2022). "We showed that inhibition of WNK1 reduces tumor volume and dispersion of metastatic cells in a mouse xenograft model of metastatic breast cancer, in part, via a network involving Slug and AXL." (PMID 35813203, 2022). "In lung cancer (LC), the Akt-WNK1-SPAK/OSR1 axis is activated by factors in the tumor microenvironment (TME)." (PMID 36123332, 2022). "In the following sections, we discuss different mechanisms by which WNK1 has been reported to support tumor malignancy." (PMID 35813203, 2022). "Previously, we showed WNK1 is downstream of VEGF-VEGFR in embryonic angiogenesis, and endothelial WNK1-mediated tumor-induced angiogenesis promotes tumor proliferation and metastasis in zebrafish." (PMID 36292952, 2022). "In this study, we demonstrated that the downstream effectors for WNK1 are different between embryonic angiogenesis and tumor-induced angiogenesis." (PMID 36292952, 2022). "To sum up, we reveal the WNK1 downstream effectors involved in tumor-induced angiogenesis and tumor migration, and PPP2R1A acts as a tumor suppressor." (PMID 36292952, 2022). "Together, these reports indicate that WNK1 plays an important role in tumor cell growth and remodeling of extracellular matrix for tumor invasion." (PMID 32131390, 2020). "In the study, we show that WNK1 signaling pathway plays an important role in tumor-induced angiogenesis." (PMID 32131390, 2020). "We have previously reported that VEGF regulates wnk1 expression, which likely explains the finding of WNK1 production in tumor as well as in tumor-transplanted fish." (PMID 32131390, 2020). "Our findings from using WNK1 and OSR1/SPAK inhibitors support the notion that OSR1/SPAK acts downstream of WNK1 for tumor angiogenesis and tumor growth." (PMID 32131390, 2020). "Knockdown of wnk1 in zebrafish decreased tumor-induced ectopic vessel formation and inhibited tumor proliferation." (PMID 32131390, 2020).
tumor (continued). "Endothelial-specific overexpression of wnk1 enhanced tumorigenesis in transgenic carcinogenic fish, supporting endothelial cell-autonomous effect of WNK1 in tumor promotion." (PMID 32131390, 2020). "We also find that tumors produce WNK1 and that endogenous zebrafish wnk1 is induced by xenotransplanted tumor." (PMID 32131390, 2020). "Supporting the notion that wnk1 is important for tumor angiogenesis, the average number and length of ectopic vessels in wnk1 morphants were much lower compared to controls." (PMID 32131390, 2020). "Overall, functional diversity of WNK1 provides multiple positive feedback loops for amplification of tumor growth." (PMID 32131390, 2020). "Our data indicate a further role for WNK1 in the regulation of alternative splicing of tumor-related RAC1B, through complex formation with GSK3β and SRPK1." (PMID 33315986, 2020). "Inhibition of WNK1 signaling cascade either by gene knockdown or oral admini stration of inhibitors decreases tumor-induced angiogenesis, proliferation and growth of tumor." (PMID 32131390, 2020). "We designed experiments to examine the role of WNK1 in tumor-induced angiogenesis using xenotransplantation in zebrafish." (PMID 32131390, 2020). "Using drugs that inhibit VEGF as well as the wnk1 morpholino antisense oligonucleotides, we will test the feasibility of using anti-wnk1 MOs to inhibit angiogenesis, tumor growth and metastasis." (PMID 25171174, 2014). "WNK1 can promote tumor proliferation through the WNT/β-Catenin signaling pathway." (PMID 40510161, 2025). "Notably, several target genes—including WNK1, CDK6, NCOA3, and NFAT5—are functionally linked to key oncogenic processes such as tumor growth, proliferation, and metastasis (eFigure 7A in Supplement 1)." (PMID 40737022, 2025). "The WNK1 gene was then knocked down in tumor cells using the siRNA transfection approach." (PMID 40510161, 2025). "Given the broad expression of WNK1 pathway proteins, our study suggests that ion and water influx are likely to be essential for migration in many cell types, including leukocytes and metastatic tumor cells." (PMID 38057317, 2023). "The connection revealed here between AXL and WNK1 raises the possibility that WNK1 may be a therapeutic option in other AXL-dependent tumor types as well." (PMID 35813203, 2022). "WNK1 is a pro-angiogenic factors that leads to tumor progression." (PMID 35499045, 2022). "Given that WNK1 plays a role in embryonic angiogenesis and may have multiple tumor-promoting effects, in this study we investigate the role of WNK1 in tumor-induced angiogenesis and the overall effect of WNK1 inhibition on tumor growth and metastasis." (PMID 32131390, 2020). "We further examined the effect of wnk1 knockdown on tumor cell proliferation." (PMID 32131390, 2020). "Thus, WNK1 can promote tumorigenesis by multiple effects that include stimulating tumor angiogenesis." (PMID 32131390, 2020). "For example, miR-524-5p inhibits angiogenesis in CRC by targeting WNK1, reducing tumor cell proliferation, inducing cell cycle arrest, and decreasing the production of vascular endothelial growth factor, thereby exhibiting inhibitory effects on tumor growth in both in vitro and in vivo experiments." (PMID 40282754, 2025). "Therefore, TRPC6-NFATc1 pathway mediated by WNK1-PI4KIIIa through PLC-β signal may play a key role in the tumor growth of ccRCC, and this mechanism can provide a potential new target for the treatment of renal cell carcinoma in the future." (PMID 37576896, 2023). "However, its expression is downregulated in HCC, and restoring its expression could inhibit WNK1/Akt-induced tumor metastasis." (PMID 36123332, 2022). "Therefore, WNK1 may affect tumor cell proliferation and angiogenesis by activating Wnt/β-catenin signaling." (PMID 32131390, 2020). "WNK1 also regulates Wnt signaling by preventing degradation of β-catenin and inhibition of WNK signaling prevented tumor growth in mice." (PMID 38672602, 2024).
tumor (continued). "In vivo experiments in murine orthotopic PCa models further confirmed that the FOXF1-WNK1-ERK5 axis contributes to tumor growth and peritoneal metastasis, which can be inhibited by knockdown of ERK5 or WNK1." (PMID 36123332, 2022). "Because WNK1 activates OSR1/SPAK, if the osr1a/osr1b or stk39 are involved in tumor-induced angiogenesis, they are supposed to be upregulated from 2 dpi to 3 dpi." (PMID 36292952, 2022). "Compared with normal tissues, CASP6, GPX4, NOD2, and WNK1 were upregulated in HCC samples, presenting low- to medium-intensity expressions, and high expression of CYCS emerged in tumor tissues." (PMID 35368686, 2022). "In zebrafish models of CRC and HCC, treatment with WNK1-SPAK/OSR1 axis inhibitors WNK463 and Closantel significantly reduced the expression of CCND1 and MMP9, and inhibited tumor metastasis and angiogenesis." (PMID 36123332, 2022). "However, the role of WNK1 in tumor-induced angiogenesis remains unknown." (PMID 32131390, 2020). "In a murine tumor model, SPARC treatment significantly induced phosphorylation of Akt and WNK1 in lung tumor nodules when compared to control mice." (PMID 28969021, 2017). "It has been demonstrated that inhibition of WNK1 by a specific inhibitor WNK463 effectively reduces the expression level of the senescence marker β-galactosidase and affects an oncogene MYC transcription, in tumor cells." (PMID 40510161, 2025). "Additionally, a chemical inhibitor of WNK1 downstream protein, such as oxidative-stress-responsive kinase 1 (OSR1), suppresses tumor-derived vessel formation in zebrafish embryos." (PMID 35326412, 2022). "Tumor cells produce VEGF, which plays a role in transcriptional regulation of wnk1 expression." (PMID 32131390, 2020). "The seven in absentia homolog 2 (SIAH2)/with-no-lysine kinase 1 (WNK1) signaling axis has emerged as a potential regulator of these processes, yet its functional role in CRC metabolism and tumor-stroma crosstalk remains incompletely understood." (PMID 41596707, 2026). "Take WNK1 as an example, the increased expression of WNK1 only promoted the enrichment of CD8+ T cells but could not decrease tumor purity." (PMID 35368686, 2022).
Cardiovascular Diseases (3 papers, 2020 to 2021). "Analyzed genes were associated with cardiovascular diseases and risk factors (TBC1D22A, WNK1), bone mineral density (HDAC5), body weight (PABPC3), glycerophospholipid metabolism (CDS2), Notch signaling (HDAC5), RNA transport and degradation (PABPC3)." (PMID 32344947, 2020).
infection (3 papers, 2008 to 2022). The state of being infected such as from the introduction of a foreign agent such as serum, vaccine, antigenic substance or organism. "During the late stage of infection, higher protein levels of PTGER4 and WNK1 were detected in Alkbh5-deficient neutrophils." (PMID 35764614, 2022). "We show here that the induction of nlp-29 expression after infection also requires wnk-1, acting upstream or in parallel to gpa-12 and to a lesser extent gck-3." (PMID 27129311, 2016).
cardiac diseases (1 paper, 2021). "In the heart, WNK1 is the predominant isoform expressed, but studies of WNK1 in cardiac diseases are lacking." (PMID 34869947, 2021).
metabolic disorders (1 paper, 2020). "Expression of some of these genes (IL6R, WNK1, GRN) has been previously reported to correlate with metabolic disorders." (PMID 32956382, 2020).
WNK1 also shares sentences with these, for which no sentence is quoted: essential hypertension (5 papers); metabolic acidosis (3); age-related hearing loss (2); autonomic dysfunction (2); neurodegenerative disease (2); Sensory neuropathy (2); Acidosis (1); acute lymphoblastic leukemia (1); acute myeloid leukemia (1); age (1); and motor neuron diseases (1); arthropathy (1); atherosclerosis (1); atrial fibrillation (1); cerebral edema (1); cerebral malaria (1); chronic myeloid leukaemia (1); colon adenocarcinoma (1); colorectal adenocarcinoma (1); coronary artery disease (1); Cyanosis (1); dependent (1); diabetes mellitus (1); epilepsy (1); esophageal cancer (1); gastric cancer (1); Gitelman syndrome (1); head and neck squamous cell carcinoma (1); hemorrhage (1); hereditary disease (1).
A further 31 diseases each share a sentence with WNK1 in 1 paper.